PPARD (peroxisome proliferator activated receptor delta)
Diseases named in the same sentence as PPARD in open-access papers (continued):
Sharing a sentence is not in itself a finding about the gene and the disease.
atopic dermatitis (6 papers, 2011 to 2025). "PPARδ was upregulated in the skin in murine models of psoriasis vulgaris and atopic dermatitis, indicating that PPARδ could be a potential therapeutic target in atopic skin." (PMID 39451206, 2024). "Interestingly, the amounts of arachidonic acid, PGF2α and 5-HETE (PPARδ endogenous ligands) are increased in lesional skin of atopic dermatitis patients when compared to healthy skin." (PMID 34298981, 2021). "Thus, the upregulation of PPARδ in the epidermis of patients with lesional atopic dermatitis might promote peroxisomal β-oxidation of very- and ultra-long-chain fatty acids and ceramides, hence significantly contributing to disease pathogenesis." (PMID 34298981, 2021). "Thus, antagonizing PPARδ to correct metabolic abnormalities in lesional atopic dermatitis and psoriasis plaques might be a new and effective therapeutic strategy to reduce both epidermal hyperplasia and consumption of structural lipids of the stratum corneum lipid matrix." (PMID 34298981, 2021). "PPARδ is upregulated in the epidermis of lesional atopic dermatitis when compared to non-lesional skin but to a lesser extent than in psoriatic lesions." (PMID 34298981, 2021). "Moreover, PPARδ gene targets were mainly induced indicating that RAR-mediated signaling and certain pathways/molecules involved in PPARδ signaling are altered in allergic dermatitis skin." (PMID 23977003, 2013).
bladder cancer (6 papers, 2017 to 2024). "Bioinformatic database screening for bladder cancer followed by gene co-expression network analysis revealed six new genes (PPARD, CST4, CSNK1E, PTPN14, ETV6, and ADRM1) and several new miRNAs, including miR-124, as drivers in the development and progression of bladder cancer." (PMID 36362406, 2022). "Importantly, human bladder cancer samples appear to express both PPARD and PPARG and our data suggest both are activated by mutant RXRA and play a role in transcriptional hyperactivity in human bladder cancer cells." (PMID 29143738, 2017). "Thus, both PPARD and PPARG contribute to mutant RXRA-mediated transcriptional hyperactivity in human bladder cancer cells and appear to have redundant function." (PMID 29143738, 2017).
fibrosis (6 papers, 2014 to 2024). the formation of excess fibrous connective tissue in an organ or tissue in a reparative or reactive process. "Normalizing cardiac PPARδ protein improves cardiac fibrosis in rats with streptozocin (STZ)-induced diabetes." (PMID 31032335, 2018). "In confirmation of our hypothesis, we show that specific CpGs within TGFβ1 (CpG2) and PDGFα (CpG3) are significantly more methylated in patients with mild fibrosis whereas PPARα (CpG3) and PPARδ (CpG2) show considerably less methylation in the same group." (PMID 25859289, 2015). "It is interesting that another study on the effect of permanent myocar-dial infarct in rats shows functional effects of PPARδ agonist (GW0742) treatment, but with augmented cardiac fibrosis with no functional consequece." (PMID 31032335, 2018).
Glucose intolerance (6 papers, 2014 to 2024). Glucose intolerance (GI) can be defined as dysglycemia that comprises both prediabetes and diabetes. "Our results suggest that polyphenol compounds present in VFP or VFPE act as ligands for PPARδ in skeletal muscle, increasing mitochondrial content, increasing whole-body oxygen consumption and metabolic flexibility, and preventing glucose intolerance, body weight gain, and excess fat mass accretion." (PMID 37175691, 2023).
liver disease (6 papers, 2009 to 2025). "This review focuses mainly on PPARD, summarizing its general function in the liver, the status of clinical trials of related drugs, and its potential as a therapeutic target for liver disease." (PMID 39899669, 2025). "Peroxisome proliferator–activated receptor delta (PPARδ) agonists have been shown to exert beneficial effects in liver disease and reduce total bile acid levels." (PMID 35605662, 2022). "A precise explanation for PPARδ gene expression decrease in experimental liver disease is difficult." (PMID 19144177, 2009). "As the pan-PPAR agonist bezafibrate altered circadian rhythms of feeding and locomotor behavior in mice, PPARD agonists could be applied to “reset” the dysregulated clocks in patients with liver disease." (PMID 39899669, 2025). "Seladelpar, a selective peroxisome proliferator-activated receptor δ (PPARδ) agonist, improves markers of hepatic injury in human liver diseases, but histological improvement of nonalcoholic steatohepatitis (NASH) and liver fibrosis has been challenging with any single agent." (PMID 38014444, 2024). "Our previous study showed that the selective PPARD agonist seladelpar (MBX-8025) alleviates ethanol-induced liver disease in mice by reducing the total bile acid pool and bile acid concentrations in the liver, small intestine, and systemic circulation, and changes bile acid composition." (PMID 35605662, 2022).
myocardial ischemia (6 papers, 2017 to 2025). A disorder of cardiac function caused by insufficient blood flow to the muscle tissue of the heart. "The cardiac protective effect of PPARδ is further supported by studies in animal models with myocardial ischemia/reperfusion (IR) injury." (PMID 31032335, 2018). "The merits of PPARδ activation by agonists have been suggested in rat models of myocardial ischemia/reperfusion injury, in addition to the reduction of oxidative stress-induced apoptosis in H9c2 cells." (PMID 28672855, 2017).
Stroke (6 papers, 2011 to 2023). Sudden impairment of blood flow to a part of the brain due to occlusion or rupture of an artery to the brain. "ERK5 signaling, a MAP kinase family member, induces PPARδ, which is protective against stroke-induce brain injuries and its agonists are suggested as potential stroke treatments." (PMID 36620775, 2022). "Although not tested with respect to protection against stroke-induced injury, PPARδ has been shown to promote survival of neurons under stress conditions." (PMID 22135673, 2011).
cholestasis (5 papers, 2024 to 2026). Impairment of the bile flow caused by obstruction within the liver, or outside the liver in the bile duct system. "Seladelpar (MBX-8025) is a selective PPARD agonist with anti-inflammatory and cholestasis inhibitory effects." (PMID 39899669, 2025). "The potent induction of FGF21 by PPARA and the effect of its agonist on cholestasis are already known, and the linkage between PPARD and PPARA in the regulation of cholestasis is a subject for future research." (PMID 39899669, 2025).
Coronary Artery Disease (5 papers, 2008 to 2023). "Previous studies revealed that PPARD polymorphisms were associated with lipid levels, metabolic traits, obesity and risk of coronary heart diseases (CHD) and cancers." (PMID 32198386, 2020).
endometrial cancer (5 papers, 2011 to 2024). Primary or metastatic malignant neoplasm involving the endometrium (mucous membrane that lines the endometrial cavity). "PPARD expression has been described in squamous head and neck cancers and in endometrial cancer." (PMID 21284875, 2011).
glioma (5 papers, 2017 to 2025). A benign or malignant brain and spinal cord tumor that arises from glial cells (astrocytes, oligodendrocytes, ependymal cells). "In our study, we firstly observed that PPARD polymorphisms (rs2016520, rs67056409 and rs1053049) were significantly associated with glioma risk." (PMID 32198386, 2020). "For the subjects older than 40 years old, rs2016520, rs67056409 and rs1053049 of PPARD significantly decreased risk of glioma in multiple models (P < 0.05)." (PMID 32198386, 2020). "Then, we divided glioma patients to astrocytoma and others, we found that rs2016520, rs67056409 and rs1053049 of PPARD were significantly associated astrocytoma risk compared with other glioma (P < 0.05)." (PMID 32198386, 2020). "After FDR correction, we found that PPARD polymorphisms were significantly associated with glioma risk, and the effects were dependent on age (P < 0.05, FDR- P < 0.05)." (PMID 32198386, 2020). "Stratified analysis showed rs2016520, rs67056409, rs1053049 of PPARD significantly decreased risk of glioma in the subgroup of age > 40 and astrocytoma (P < 0.05)." (PMID 32198386, 2020). "We found PPARD polymorphisms (rs2016520, rs67056409, rs1053049) were significantly associated with glioma risk in multiple models (P < 0.05)." (PMID 32198386, 2020). "In conclusion, we found genetic polymorphisms of PPARD were associated with glioma risk in the Chinese Han population, which suggests the role of PPARD in the carcinogenesis of glioma." (PMID 32198386, 2020). "For male, PPARD rs1053049 had a strong relationship with glioma risk in allele (P = 0.041), dominant (P = 0.040) and additive (P = 0.040) models." (PMID 32198386, 2020). "And, stratified analysis showed the effects of PPARD polymorphisms on glioma risk were age-dependent." (PMID 32198386, 2020). "After adjustment for age and sex, PPARD polymorphisms (rs2016520, rs67056409 and rs1053049) were significantly associated with glioma risk (P < 0.05)." (PMID 32198386, 2020). "The effects of PPARD polymorphisms on glioma risk might related to SiPhy cons, Promoter histone marks, Enhancer histone marks, DNAse, Motifs changed, GRASP QTL hits, NHGRI/EBI GWAS hits, Selected eQTL." (PMID 32198386, 2020). "It suggests that PPARD polymorphisms could be involved in the susceptibility of glioma development." (PMID 32198386, 2020). "However, little is known on the relationship of PPARD polymorphisms with glioma risk and prognosis." (PMID 32198386, 2020). "Then, we assessed the association of PPARD (rs2016520, rs67056409, rs1053049 and rs2206030) and PPARG (rs2920503, rs4073770 and rs1151988) polymorphisms with glioma prognosis." (PMID 32198386, 2020). "The odd ratios (OR) and 95% confidence interval (CI) were calculated to assess the association of PPARD and PPARG polymorphisms with glioma risk." (PMID 32198386, 2020). "Then, we conducted log-rank test, Kaplan-Meier analysis and Cox regression model to evaluate the relationship of PPARD and PPARG polymorphisms with glioma prognosis." (PMID 32198386, 2020). "Our findings suggested that PPARD and PPARG polymorphisms were associated with glioma risk and prognosis in the Chinese Han population, and further studies are need to confirm our results." (PMID 32198386, 2020). "In this case-control study, we examined the association of PPARD and PPARG polymorphisms with glioma risk and prognosis in the Chinese Han population." (PMID 32198386, 2020). "We conducted a case-control study to investigate the association of polymorphisms in PPARD and PPARG with glioma risk and prognosis in the Chinese Han population." (PMID 32198386, 2020). "Seven polymorphisms (PPARD: rs2016520, rs67056409, rs1053049 and rs2206030; PPARG: rs2920503, rs4073770 and rs1151988) were genotyped using the Agena MassARRAY system in 568 glioma patients and 509 healthy controls." (PMID 32198386, 2020). "Then, we explored the association of PPARD and PPARG polymorphisms with OS and PFS of glioma patients." (PMID 32198386, 2020).
glioma (continued). "We further did stratification analysis of PPARD and PPARG polymorphisms with glioma risk." (PMID 32198386, 2020). "Therefore, we conducted a case-control study to investigate the association of PPARD and PPARG polymorphisms (rs2016520, rs67056409, rs1053049, rs2206030, rs2920503, rs4073770 and rs1151988) with glioma risk and prognosis in the Chinese Han population." (PMID 32198386, 2020). "Recent studies showed that peroxisome proliferator-activated receptors (PPARs) had effects on the progression of multiple tumors, but the role of PPARD and PPARG in glioma remains poorly understand." (PMID 32198386, 2020). "Further studies in larger samples with more ethnic groups are needed to validate our results and explore the mechanism of PPARD and PPARG in glioma." (PMID 32198386, 2020). "Third, the molecular mechanisms of PPARD and PPARG on glioma risk and prognosis are not elucidated in our study." (PMID 32198386, 2020). "Moreover, we did not observe significantly association of PPARD and PPARG polymorphisms with OS and PFS of glioma patients (P > 0.05)." (PMID 32198386, 2020). "It demonstrated that PPARD and PPARG polymorphisms might not contribute the prognosis of glioma." (PMID 32198386, 2020).
liver inflammation (5 papers, 2021 to 2024). "After treatment with the PPARδ agonist seladelpar (MBX-8025) (ClinicalTrials.gov identifier: NCT03551522), liver biopsy samples exhibited interface hepatitis in a phase 2 NASH trial." (PMID 35453652, 2022).
lupus (5 papers, 2017 to 2023). "It is reported that the genetic deletion of PPARD (encode PPAR-δ which was expressed on macrophages) in mice presented with lupus manifestations." (PMID 32566688, 2020). "From the 15 drugs obtained, PPARD is the TF that is associated with 12 of these drugs, most of them related to Perixosome proliferator receptor (PPAR), which has been described to be associated with Lupus-like autoimmunity development (see discussion)." (PMID 33915751, 2021).
type 1 diabetes (5 papers, 2010 to 2018). "Next, we discovered eight gene polymorphisms (ORMDL3, SPHK2, B4GALNT1, SLC1A5, GALC, PPARD, PPARG and B4GALT1) involved in sphingolipid metabolism that contribute to the genetic predisposition to type 1 diabetes." (PMID 29671030, 2018). "For six genes (ORMDL3, GALC, SPHK2, SLC1A5, PPARD and B4GALT1) the SNPs with the strongest association with type 1 diabetes (lowest p value) also acted as cis-eQTLs, suggesting that these SNPs regulate the expression of their associated genes." (PMID 29671030, 2018). "Using streptozotocin to induce type 1 diabetes rat model, we measured PPARδ expression and downstream targets." (PMID 27519769, 2016).
Anxiety (4 papers, 2015 to 2022). Intense feelings of nervousness, tension, or panic often arise in response to interpersonal stresses. "Because of the putative involvement of hippocampal neurogenesis in the control of anxiety and depressive-like states, we next assessed the effect of PPARδ overexpression or activation on neurogenesis in CMS mice using BrdU labeling analysis." (PMID 26362775, 2015). "Novelty-suppressed feeding (NSF) and elevated plus maze (EPM) tests were performed to observe the effect of PPARδ overexpression on anxiety-like behavior in mice exposed to CMS." (PMID 26362775, 2015).
colorectal tumors (4 papers, 2006 to 2009). "Increased levels of PPARδ expression have already been observed in rodent colorectal tumors and in primary human colorectal adenocarcinomas." (PMID 17767717, 2007). "To elucidate further the expression and role of PPARδ in human colorectal tumour, we examined expression of PPARδ in multistage carcinogenesis of the colorectum and found that PPARδ expression increased from normal mucosa to adenomatous polyps to cancer tissues." (PMID 16969348, 2006).
congestive heart failure (4 papers, 2017 to 2023). Failure of the heart to pump a sufficient amount of blood to meet the needs of the body tissues, resulting in tissue congestion and edema. "Therefore, it needs to be tested if the pro-regenerative effect of PPARδ activation can be enhanced by GSK3β inhibitors in vivo, as we have observed in vitro, and whether this treatment is effective if applied after injury or during chronic heart failure." (PMID 28621328, 2017).
diabetic nephropathy (4 papers, 2008 to 2022). "Previous studies indicated that PPARδ negatively regulated the transcription of NF-κB, such as in inflammation or in diabetic nephropathy." (PMID 29416623, 2018). "We have demonstrated that activation of nuclear hormone receptors, including peroxisome proliferator-activated receptor (PPAR) γ, PPARδ and liver x receptor, inhibits macrophage infiltration and inflammation, and ameliorates diabetic nephropathy in animal models." (PMID 24960177, 2014).
Duchenne muscular dystrophy (4 papers, 2011 to 2022). Duchenne muscular dystrophy (DMD) is a neuromuscular disease characterized by rapidly progressive muscle weakness and wasting due to degeneration of skeletal, smooth and cardiac muscle. "PPARδ has also been implicated in the treatment of degenerative muscle diseases such as Duchenne muscular dystrophy (DMD), which is caused by the mutation of the dystrophin gene." (PMID 22040534, 2011).
gastric adenocarcinoma (4 papers, 2016 to 2023). "In stomachs, PPARδ significantly increases chemokine Ccl20 expression in gastric epithelial cells while inducing gastric adenocarcinoma (GAC)." (PMID 37572185, 2023). "The H pylori cag secretion system activates beta-catenin, p120, and PPARδ, which promote gastric epithelial cell proliferation and might therefore contribute to gastric adenocarcinoma development in humans." (PMID 27198692, 2016).
intestinal tumors (4 papers, 2006 to 2024). "GW501516 treatment significantly decreased CD8+ T -cell proliferation and IFNγ-expressing CD8+ T cells in intestinal tumors and matched normal tissues compared with the control group, suggesting PPARδ regulates CD8+ T-cell activation." (PMID 39292167, 2024).
metastatic tumors (4 papers, 2014 to 2025). "In vivo models, the subcutaneous tumor of the PPARD-OE group was bigger than that in the PPARD knock-out group and API-2 group compared to the control group, as well as that the liver metastatic tumor in the PPARD-OE group was bigger than the other groups with MCF-7 cells." (PMID 39922804, 2025). "Genetic alterations in metabolic genes associated with metastatic progression analyzed, revealed that genes involved in cellular fatty acid uptake (CAV1, CD36) and de novo lipogenesis (PPARA, PPARD, MLXIPL) were specifically amplified at higher frequencies in metastatic tumors." (PMID 28798698, 2017). "However, genes involved in cellular FA uptake (CAV1, CD36) and de novo lipogenesis (PPARA, PPARD, MLXIPL) were specifically amplified at higher frequencies in metastatic tumors." (PMID 26725848, 2016). "However, 6 genes were amplified at significantly higher frequencies in metastatic tumors: SCO2 (p = 1.1 × 10−9), MLXIPL (p = 2.1 × 10−4), PPARA (p = 1.2 × 10−10), PPARD (p = 4 × 10−15), CAV1 (p = 3.4 × 10−4) and CD36 (p = 3.5 × 10−4)." (PMID 26725848, 2016).
osteoarthritis (4 papers, 2019 to 2024). A noninflammatory degenerative joint disease occurring chiefly in older persons, characterized by degeneration of the articular cartilage, hypertrophy of bone at the margins and changes in the synovial membrane. "Within tier 1, ten candidates have previously been studied in clinical trials of efficacy or in cohort studies of osteoarthritis (six arising from new signals: PPARD, NR3C1, VDR, MAPK14, IGF1R, and CHST3)." (PMID 34450027, 2021). "Osteoarthritis (OA) is the most prevalent degenerative joint disease, and PPARs are involved in its pathogenesis; however, the specific mechanisms by which changes in PPARδ impact the OA pathogenesis yet to be discovered." (PMID 38576477, 2024). "The PPARD antagonist sulindac has marketing authorization as a non-steroidal anti-inflammatory drug (NSAID) in osteoarthritis for its prostaglandin synthase activity." (PMID 34450027, 2021).
acute renal failure (3 papers, 2012 to 2022). "By increasing peroxisome function, SIRT1 activation, which is reciprocally stimulated by upregulated PPARα and PPARδ, can prevent the drug-induced renal cell apoptosis and acute kidney injury in mice." (PMID 31321239, 2019). "Deficiency of PPARδ increases susceptibility to ischemic injury in the kidney, while selective agonists of PPARδ protect against ischemic acute renal failure." (PMID 22448165, 2012).